METTL3 (methyltransferase 3, N6-adenosine-methyltransferase complex catalytic subunit)
Diseases named in the same sentence as METTL3 in open-access papers (continued):
Sharing a sentence is not in itself a finding about the gene and the disease.
ovarian carcinoma (continued). "The latest studies have shown that PI3K/AKT/mTOR can also be activated by METTL3-mediated M6A modification in ovarian cancer and retinoblastoma." (PMID 35574388, 2022). "Mechanism analysis shows that METTL3 promotes ovarian carcinoma growth and invasion through upregulating the receptor tyrosine kinase AXL translation and epithelial to mesenchymal transition." (PMID 35813486, 2022). "Compared with ovarian cancer, METTL3 plays as a tumor suppressor in the pathogenesis of endometrial cancer." (PMID 33879256, 2021). "The results showed that the mRNA and protein expression levels of METTL3 in ovarian cancer tissues were significantly increased compared with adjacent normal tissues." (PMID 34497267, 2021). "Differential analysis of GSE66957, a relevant gene expression microarray for ovarian cancer, indicated that METTL3 was significantly highly expressed in ovarian cancer." (PMID 34497267, 2021). "Taken together, our results provide evidence to support the proposition that METTL3 plays a carcinogenic role in ovarian cancer." (PMID 34497267, 2021). "Recent studies indicate that METTL3 expression correlates with ovarian carcinoma cellular proliferation and migration through the regulation of AXL transcription." (PMID 34497267, 2021). "Next, we aimed to determine the effect of METTL3 on the proliferation, migration, invasion, and apoptosis of ovarian cancer cells." (PMID 34497267, 2021). "At the same time, METTL3 effectively downregulated the overall m6A level, suggesting that METTL3 plays an oncogenic part in ovarian cancer." (PMID 34794452, 2021). "Future studies will explore the possibility of regulating the METTL3/miR-1246/CCNG2 axis as targeted therapies for ovarian cancer." (PMID 34497267, 2021). "METTL3 can promote the proliferation and migration of ovarian cancer cells by regulating the transcription of AXL." (PMID 34497267, 2021). "METTL3 downregulated the BCL-2-related apoptotic pathway to resist the apoptosis of ovarian cancer cells." (PMID 33879256, 2021). "GSEA analysis demonstrated that the expressions of METTL3, YTHDC1, RBM15B, HNRNPC, IGF2BP2, RBMX, and ZC3H13 were correlated with a higher number of multiple Hallmark pathways in ovarian cancer." (PMID 33225598, 2021). "In ovarian cancer, METTL3 activity has been reported to accelerate cell proliferation and migration by regulating transcription of AXL receptor tyrosine kinase (AXL, referring to the Greek term “anexelekto”, which means uncontrolled)." (PMID 34497267, 2021). "The current study highlights the promoting role of METTL3 in the development of ovarian cancer, and presents new targets for its treatment." (PMID 34497267, 2021). "Hua’s group unveiled that methyltransferase-like 3 (METTL3) was up-regulated in ovarian cancer and promoted growth and invasion of ovarian cancer cells via stimulating the receptor tyrosine kinase AXL translation." (PMID 34616622, 2021). "Mechanistically, METTL3 aggravated ovarian cancer by targeting miR-1246, while miR-1246 targeted and inhibited CCNG2 expression." (PMID 34497267, 2021). "Decreased METTL3 inhibited the proliferation and migration of ovarian cancer cells and promoted apoptosis, while METTL3 overexpression exerted opposite effects." (PMID 34497267, 2021). "METTL3 is highly expressed in ovarian cancer, significantly correlating with ovarian cancer grade, PT status, PN/PM status, and FIGO staging." (PMID 34336690, 2021). "Upregulation of METTL3 is also observed in patients with ovarian cancer which is correlated with poor overall patient survival." (PMID 32194861, 2020). "Ovarian cancer cells with METTL3 overexpression exhibited increased cellular proliferation, invasiveness, metastasis and tumorigenicity in nude mice; which upon METTL3 silencing showed the opposite effects." (PMID 32194861, 2020). "METTL3 exerted the oncogenic effect in ovarian cancer cells by increasing the protein level of EMT-inducing AXL protein in cellular cytoplasm." (PMID 32194861, 2020).
ovarian carcinoma (continued). "In this context, “readers” such as METTL3 and VIRMA have been associated with apoptosis inhibition, migration, and invasion in ovarian cancer, while FTO leads to reduced “stemness” in ovarian cancer cell lines and YBX1 renders malignant cells susceptible to the cytotoxic effects of cisplatin." (PMID 41301911, 2025). "Moreover, ASO-mediated inhibition of the circular RNA circPLPP4 overcomes cisplatin chemoresistance in ovarian cancer by modulating the METTL3/PI3K-AKT signaling pathway." (PMID 41157107, 2025). "Moreover, the METTL3–YTHDF1–m6A signaling axis functions as a pivotal driver in ovarian cancer progression." (PMID 40986143, 2025). "Likewise, in ovarian carcinoma, cytoplasmic METTL3 promotes AXL translation, contributing to the initiation and progression of ovarian cancer." (PMID 38444581, 2024). "In ovarian cancer cells, METTL3 served as an oncogenic gene promoting tumor growth and invasion." (PMID 38281945, 2024). "METTL14 can assist METTL3 in substrate recognition and expressed at low levels in ovarian cancer." (PMID 37194218, 2023). "METTL3 has been shown in various studies to contribute to the tumorigenesis of ovarian cancer." (PMID 37194218, 2023). "METTL3 may serve an oncogenic role in the progression of ovarian cancer partially through the PI3K-AKT signaling pathway." (PMID 39872957, 2023). "Similarly, METTL3 also drove proliferation in ovarian cancer through regulation of the receptor tyrosine kinase AXL; however, the regulatory mechanism by which METTL3 up-regulates AXL was not established." (PMID 35350378, 2022). "Mechanistically, PLAA inhibited METTL3 expression through the ubiquitin-mediated degradation and destabilized TRPC3 expression via METTL3-mediated m6A modification, which consequently suppressed intracellular calcium concentration and ovarian cancer metastasis." (PMID 35869392, 2022). "METTL3 showed hypomethylation and high expression in ovarian cancer tissues and cells." (PMID 34497267, 2021). "METTL3 has been reported to promote tumor progression of ovarian cancer." (PMID 33879256, 2021). "METTL3 was previously reported as a tumor-promoting factor in ovarian cancer, in accordance with our present results that overexpression of METTL3 could accelerate proliferation, migration, and invasion, while inhibiting apoptosis of ovarian cancer cells." (PMID 34497267, 2021). "METTL3 also participated in the regulation of oncogenic pathways in ovarian cancer." (PMID 33879256, 2021). "Besides, there was a reduction (~34%) of METTL3 mRNA expression but unchanged METTL14 mRNA expression in ascites NK cells of ovarian cancer patients." (PMID 34535671, 2021). "To parse out the role of METTL3 in ovarian carcinoma, we first detected the mRNA and protein expression of METTL3 in ovarian cancer tissues and adjacent normal tissues of 64 patients with ovarian cancer by RT-qPCR, immunohistochemistry, and Western blot analysis." (PMID 34497267, 2021). "Our study demonstrated that the expression and methylation level of METTL3 has a tight relationship with ovarian cancer development and further identified that METTL3 stimulated the m6A modification of miR-1246 to promote miR-1246 expression, which subsequently downregulates the expression of CCNG2." (PMID 34497267, 2021). "Besides, RT-qPCR data revealed that miR-1246 was highly expressed in ovarian cancer tissues, and a correlation analysis demonstrated that the expression of miR-1246 was positively correlated with that of METTL3." (PMID 34497267, 2021). "Collectively, we show that METTL3 can promote the maturation of pri-miR-1246 and upregulate the expression of miR-1246 through m6A modification, thereby promoting proliferation, migration, and invasion of ovarian cancer cells while inhibiting their apoptosis." (PMID 34497267, 2021).
ovarian carcinoma (continued). "In our study, we mainly focused on EOC, an epithelial ovarian cancer, and found that silent METTL3 could inhibit cell viability and proliferative capacity, promote apoptosis, and induce cell cycle arrest in the G0/G1 phase, indicating that METTL3 performed a similar role in EOC as it did in OC." (PMID 38025760, 2023). "Finally, we shifted our attention to determine whether METTL3 affects the proliferation, migration, and invasion of ovarian cancer cells through the miR-1246/CCNG2 axis." (PMID 34497267, 2021). "Therefore, our study focused on whether METTL3 played a role by the regulation of miR-1246 in ovarian cancer cells." (PMID 34497267, 2021). "Our results showed that the METTL3 genome sequence was hypomethylated in ovarian tumor samples and cells, indicating that a high level of METTL3 correlated with poor prognosis of patients with ovarian cancer, and suggesting that METTL3 might participate in ovarian cancer development." (PMID 34497267, 2021). "The gut microbiota can regulate the expression of host RNA m6A (N6-methyladenosine) modification enzymes (such as METTL3 and FTO), affecting the translation efficiency and stability of ovarian cancer-related genes." (PMID 40732683, 2025). "Suppression of METTL3 and IGF2BP2 mRNA and protein levels.Reduced cell proliferation and migration for ovarian cancer models." (PMID 41157107, 2025). "We demonstrated that MEG3 is influenced by METTL3/YTHDF2 methylation and restrains ovarian cancer proliferation and metastasis by binding miR-885-5p to increase VASH1 expression." (PMID 38281945, 2024). "In another study, phospholipase A2 activating protein (PLAA) degraded METTL3 via the ubiquitination pathway, which resulted in the destabilization of the m6A-modified mRNA oncogene TRPC3 and prevented the metastasis of ovarian cancer cells." (PMID 37194218, 2023). "Downregulation of METTL3 inhibited cell proliferation, colony formation, and invasion, induced apoptosis, and suppressed AKT pathway activation in ovarian cancer." (PMID 37194218, 2023). "According to the study, IGF2BP2, KIAA1429, and YTHDF1 regulators are highly amplified in OC, and the majority of m6A genes, including METTL3, KIAA1429, HNRNPC, ZC3H13, and IGF2BP2, are upregulated in ovarian cancer tissues." (PMID 37194218, 2023). "METTL3 also inhibits the expression of CCNG2 by promoting pri-microRNA-1246 maturation, thereby promoting the occurrence and metastasis of ovarian cancer." (PMID 35945641, 2022). "In another study using a larger cohort of 162 ovarian carcinoma samples, METTL3 expression was positively correlated with tumor histological grades pT, pN, pM and FIGO stage, suggesting that METTL3 is important for metastasis of ovarian cancer." (PMID 36008936, 2022). "In further studies, we focused on METTL3 expression in normal ovarian epithelial IOSE80 cells and ovarian cancer cells, i.e., A2780, OVCAR3, SKOV3, and ES2." (PMID 34497267, 2021). "In this study, we mainly analyzed the interaction among METTL3, miR-1246, and CCNG2 and identified their effects on progression in ovarian cancer." (PMID 34497267, 2021). "Importantly, there was a distinct reduction in METTL3 methylation in the tumor samples, but no such was changed in paracancerous tissues, suggesting that extensive hypomethylation of METTL3 in ovarian cancer was negatively associated with the survival of patients with this carcinoma." (PMID 34497267, 2021). "Indeed, METTL3, METTL14, and FTO have been clarified to affect the progression of ovarian cancer in a m6A-dependent manner." (PMID 39617776, 2024). "In this study, we comprehensively demonstrated that lncRNA MEG3 is regulated by METTL3-mediated YTHDF2 methylation; it upregulates VASH1 through regulatory competitive binding to hsa-miR-885-5p and then inhibits ovarian cancer cell proliferation, migration, and invasion." (PMID 38281945, 2024).
ovarian carcinoma (continued). "The METTL3/YTHDF2 axis promotes degradation of tumour suppressor IFFO1 mRNA in an m6A-dependent manner to promote nucleation of β-catenin and enhance cisplatin resistance in ovarian cancer." (PMID 37194218, 2023). "METTL3 and METTL14 form a stable heterodimer to affect the metastatic potential of cancer cells via distinct mechanism, for example, METTL3 promoted the initiation and metastasis of ovarian cancer by inhibiting CCNG2 expression." (PMID 35869392, 2022). "It has been reported that METTL3 and METTL14 were downregulated in ovarian carcinoma cells." (PMID 34745970, 2021). "Two GEO databases demonstrated that 7 readers (HNRNPC, IGF2BP1, IGF2BP2, IGF2BP3, RBMX, YTHDC2, and YTHDF2) and 3 writers (METTL3, RBM15, and RBM15B) were more highly expressed in ovarian cancer than in ovarian surface epithelium or normal peritoneum tissues (GEO14407 and GEO12470)." (PMID 33225598, 2021). "Notably, the m6A writers METTL3, KIAA1429, METTL14, and WTAP constructed the hub genes in m6A RNA methylation regulator interaction network according to PPI in ovarian cancer." (PMID 34149801, 2021). "Additionally, an oe-METTL3 plasmid was transfected into ES2, OVCAR3, and IOSE80 cells to investigate further the role of METTL3 in ovarian cancer." (PMID 34497267, 2021). "Levels of the m6A methylase “writers,” including METTL3, METTL14 and WTAP, were increased in brain, central nervous system (CNS), cervical, and head and neck cancer and sarcoma but decreased in BC, lymphoma and ovarian cancer as compared with normal controls." (PMID 30953473, 2019). "Notably, the methylation of METTL3, which is mediated by PRMT5, might foster cisplatin resistance in ovarian cancer by bolstering DNA repair pathways." (PMID 40986143, 2025). "Furthermore, ASO-mediated inhibition of the small nucleolar non-coding RNA SNORD9 prevents its interaction with METTL3, downregulates NFYA mRNA expression levels, and, consequently, decreases the expression of its target genes (CCND1, CDK4, and VEGFA), suppressing ovarian cancer progression." (PMID 41157107, 2025). "However, no research has yet explored the effect of the METTL3/miR-1246/CCNG2 signaling axis in ovarian cancer." (PMID 34497267, 2021). "METTL3 may play a carcinogenic part in OC cells through the AKT signalling pathway, and downregulation of METTL3 expression leads to reduced activation of the AKT signaling pathway in ovarian cancer cells." (PMID 34794452, 2021). "No change of global m6A levels in ovarian cancer resistant cells might be due to downregulated FTO, ALKBH5, METTL3, and METTL14." (PMID 34745970, 2021).
renal cell carcinoma (50 papers, 2017 to 2026). "The GSEA pathway study revealed that METTL3 mainly regulates the cell cycle, renal cell carcinoma, and cancer pathways, which shed light on the METTL3 signaling mechanism in CRC." (PMID 40177651, 2025). "Pathway enrichment analysis revealed METTL3’s involvement in crucial pathways, including the cell cycle and renal cell carcinoma (p < 0.01)." (PMID 40177651, 2025). "Low METTL3 expression in renal cell carcinoma (RCC) suggests a tumor suppressor role, while reduced METTL14 expression weakens m6A modification on tumor suppressor transcripts (e.g. BPTF and PTEN), thereby promoting cancer cell invasion and metastasis." (PMID 41446042, 2025). "The purpose of this study was to investigate the function and regulatory mechanisms of the methyltransferase METTL3 in renal cell carcinoma (RCC)." (PMID 38233403, 2024). "METTL3 can affect cell function and serve as a novel marker for the progression and survival of renal cell carcinoma." (PMID 36118874, 2022). "For example, a study on renal cell carcinoma showed that the depletion of METTL3 promoted cell proliferation, cell growth, and colony formation." (PMID 36293529, 2022). "METTL3 also exhibits tumor suppressor function in some cases: lower expression of METTL3 was detected in renal cell carcinoma patients and predicts a favorable prognosis." (PMID 35117988, 2021). "They established a risk signature for predicting the prognosis of renal cell carcinoma based on METTL14 and METTL3." (PMID 32808488, 2020). "Li et al38 found that the expression of METTL3 in renal cell carcinoma was down‐regulated and that the decreased expression of METTL3 was related to poor prognosis." (PMID 32808488, 2020). "They further elucidated that METTL3 inhibited proliferation and metastasis in renal cell carcinoma via epithelial‐to‐mesenchymal transition (EMT) and PI3K‐Akt‐mTOR pathways." (PMID 32808488, 2020). "In another study, METTL3 was found to inhibit the development of renal cell carcinoma by inactivating the AKT signaling pathway, which is in opposition to our study." (PMID 30886897, 2019). "For instance, METTL3 may play a tumor-suppressor role in renal cell carcinoma's cell proliferation, migration, invasion, and cell cycle functions." (PMID 39103890, 2024). "However, compared to paraneoplastic tissues, renal cell carcinoma (RCC) tissues had lower METTL3 expression, which inhibited cell proliferation, migration, and invasion." (PMID 39289775, 2024). "Upregulation of METTL3 can inhibit renal cell carcinoma proliferation, migration and cell cycle." (PMID 36003776, 2022). "Similarly, the METTL3 expression level is associated PI3K/AKT/mTOR pathway molecule expression levels and is related to unfavorable outcomes in renal cell carcinoma." (PMID 34248650, 2021). "The results indicated that high METTL3 expression was associated with some essential signaling pathways including ERBB pathway, MAPK pathway, mTOR pathway, renal cell carcinoma, pathway in cancer, TGF-β pathway and Wnt pathway, giving a clue of the underlying mechanism in the pathogenesis of ccRCC." (PMID 33430867, 2021). "Consistently, increased Mettl3 expression has been shown to increase invasion of lung adenocarcinoma cells via promotion of oncogenic protein translation 17 and growth inhibition of renal cell carcinoma cells." (PMID 32483411, 2020). "However, in another study, METTL3 is identified as a tumor suppressor gene in renal cell carcinoma, inhibiting tumor proliferation, migration and the cell cycle." (PMID 30886897, 2019). "We aimed to study the role of METTL3 in renal cell carcinoma (RCC) carcinogenesis and development." (PMID 29221190, 2017). "METTL3 can promote the proliferation and metastasis of esophageal cancer cells and renal cell carcinoma (RCC) cells." (PMID 41256854, 2025). "However, in renal cell carcinoma, METTL3 acts as a tumor suppressor." (PMID 38966069, 2024).